MTOR (mechanistic target of rapamycin kinase)
Diseases named in the same sentence as MTOR in open-access papers (continued):
Sharing a sentence is not in itself a finding about the gene and the disease.
sarcopenia (continued). "Leucine, a branched-chain amino acid, functions as a potent activator of mTOR signaling independent of insulin, making it particularly valuable in insulin-resistant states common in sarcopenia and cachexia." (PMID 41220691, 2025). "In sarcopenia and OA patients, DDIT4/REDD1 modulates mTOR signalling pathways, contributing to muscle protein synthesis and degradation balance, affecting chondrocyte survival and function under stress conditions, thus playing an important role in muscle atrophy and OA." (PMID 38962732, 2024). "Furthermore, sarcopenia is correlated with lower levels of IGF-1 and lowered IGF-1 damages protein synthesis by inhibiting the phosphatidylinositol 3-kinase (PI3K)-Akt-mTOR pathway." (PMID 36632744, 2022). "Unfortunately, after liver transplantation, sarcopenia did not improve and even worsened because of immunosuppressive drugs such as steroids, calcineurin inhibitors, and mammalian target of rapamycin (mTOR) inhibitors." (PMID 33807573, 2021). "Taken together, the existing data suggest that the IGF-1/Akt/mTOR pathway does not play a primary role in the process of sarcopenia, and that other regulators will need to be identified as possible modulators of sarcopenia." (PMID 22184279, 2011). "However, to our knowledge, there is no publication where both of these proteins (mTOR and Rps6kb1) are studied in relation to sarcopenia." (PMID 39585121, 2024). "Therefore, the Akt/mTOR and FOXO1/myostatin signaling pathways may be the key to protein synthesis improvement in sarcopenia." (PMID 35250869, 2022). "Notably, the anti-aging effects of Klotho have been partially attributed to modulation of the renin-angiotensin system (RAS), Wnt, mammalian target of rapamycin (mTOR), and mitogen-activated protein kinase (MAPK) pathways, some of which are also mechanistic targets for these sarcopenia treatments." (PMID 36188832, 2021). "Therefore, we hypothesize that exercise can regulate Akt/mTOR and Akt/FoxO3a signal pathways to induce autophagy and cooperate with AMPK-mediated mitochondrial quality control to alleviate sarcopenia." (PMID 33224037, 2020). "During sarcopenia, impairment in insulin-like growth factor (IGF-1) were demonstrated in the muscles of old rats, but the activation of the IGF-1/Akt/mammalian target of rapamycin (mTOR) had shown to exhibit protective effect towards the skeletal muscle mass loss." (PMID 24349615, 2013). "Interestingly, the PI3K/AKT/mTOR pathway plays an important role in translating IGF1 signals to protein synthesis and inhibiting muscle degradation and sarcopenia, and this pathway also regulates steroid, protein, ATP, and fatty acid synthesis critical in prostate carcinogenesis." (PMID 22257467, 2012). "Therefore, although higher mTOR activation can be observed during sarcopenia following anabolic stimuli, this signal may not promote the correct assembly of the protein translation machinery, resulting in insufficient MPS." (PMID 36430301, 2022). "Although there are several signaling pathways linked to sarcopenia, we focus our discussion on the canonical and non-canonical transforming growth factor-β (TGF-β) cascade, Wnt signaling and the insulin-like growth factor-1 (IGF-1)/Akt/mammalian target of rapamycin (mTOR) pathways." (PMID 22184279, 2011). "Taken as a whole, current evidence indicates that, while the mTOR pathway is stimulated to achieve an increase in MPS and reduce MPD in sarcopenia, this does not translate into a preservation of muscle mass." (PMID 36430301, 2022).
breast tumor (117 papers, 2005 to 2025). "We examined the association between PA and protein expression in the mTOR signaling pathway in breast tumor tissue." (PMID 36895729, 2023). "The study found that guideline-concordant PA levels were associated with increased mTOR signaling pathway activity in breast tumors." (PMID 36895729, 2023). "Phosphoinositide 3-kinase (PI3K)/AKT/mTOR pathway gene variations are typically discovered in breast tumours and are linked to cellular change, carcinogenesis, cancer progression, and medication resistance." (PMID 36831624, 2023). "The mTOR pathway relies on protein phosphorylation for signaling, and phosphorylated (p) mTOR protein expression levels in breast tumors were strongly associated with BMI and body fatness." (PMID 34330319, 2021). "Here, we investigated the mTOR pathway activities in breast tumors in association with body size, i.e., BMI, waist circumference (WC), and waist/hip ratio (WHR), as well as body composition, i.e., fat mass, fat mass index, and percent body fat." (PMID 33024820, 2020). "Our study is among the few reporting the association between body fatness and mTOR pathway protein expression in breast tumors." (PMID 33024820, 2020). "The Akt pathway is a master regulator of cancer cell metabolism, components of PI3K/AKT/mTOR pathway are mutated in nearly 25% of breast tumors and are associated with drug responses in ER (+) and ER (−) tumors." (PMID 30987380, 2019). "Recently, it was reported that MRK-003 GSI treatment of Balb/c-neuT female mice reduced tumour onset, tumour burden, and AKT1/mTOR activities associated with ErbB-2-positive, murine breast tumours." (PMID 21847123, 2011). "However, the observation is inconsistent with our previous finding that higher versus lower BMI was associated with higher mTOR activities in breast tumors." (PMID 36895729, 2023). "However, our study showed the opposite result, that is, PA was associated with higher mTOR signaling pathway activity in breast tumors." (PMID 36895729, 2023). "Therefore, we concluded that in breast tumors where there is an intact estrogen regulated mTOR signaling, mTOR is associated with an increased likelihood of responsiveness to endocrine therapy." (PMID 30154572, 2018). "Taken together, these data indicate that BRCA-negative cells are addicted to AKT/mTOR pathway for their survival and inhibition of mTOR by MET could significantly suppress growth of BRCA1-deficient breast tumors." (PMID 26097796, 2012). "Moreover, the underlying mechanism of antitumor effects regarding Pt/GF@Lipo‐TPP nanocatalysts was chiefly through promoting the generation of ROS, stimulating mitochondrial dysfunction, downregulating AKT/mTOR signaling, and causing cell autophagic death in breast tumor cells." (PMID 37366463, 2021). "Sodium cantharidate stimulated autophagy and apoptosis in breast tumors by blocking the PI3K/AKT/mTOR pathway." (PMID 40740483, 2025). "miR-99a attenuates mTOR signaling resulting in inhibition of breast tumor growth through the HIF1-α pathway." (PMID 39858015, 2025). "ER and PI3K/AKT/mTOR signaling pathways are characterized by a complex interplay in breast tumors, and their coordinated activation supports the survival of ER-positive BC cells." (PMID 40507317, 2025). "Based on these findings, we postulate that mG3 breast tumors are highly proliferative, and that their proliferation is stimulated through mTOR and c-MYC signaling." (PMID 40740860, 2025). "Since, in BC, autophagy acts paradoxically, in this study, the expression of Beclin1 and mTOR genes, as autophagy markers, were evaluated in breast tumor biopsies compared to respective controls." (PMID 38164366, 2024). "The lysosomal TMEM9-LAMTOR axis has been found to play an important role in controlling mTOR signaling integrity in breast tumor development." (PMID 38420434, 2024).
breast tumor (continued). "In this study, we evaluated the gene expression of mTOR and Beclin1 and the levels of p62 protein, in breast tumors and compared them to a control condition." (PMID 38164366, 2024). "Mechanistically, LNT treatment restrained macrophage polarization from M1 to M2 phenotype and promoted autophagic cell death by inhibiting Nur77 expression, AKT/mTOR signaling, and inflammatory signals in breast tumor cells." (PMID 37249285, 2023). "We began our investigation by analyzing the PI3K/mTOR pathway, which is known to play a significant role in the survival of breast tumor cells, resistance to apoptosis, and angiogenesis." (PMID 37822691, 2023). "Here, we examined breast tumor cells and their response to antitumor agents, rho‐associated protein kinase (ROCK) and mTOR inhibitors by tomographic microscopy." (PMID 37206227, 2023). "In conclusion, we found indications of higher mTOR signaling pathway activity in breast tumor tissue among women with sufficient PA levels compared with women with no PA." (PMID 36895729, 2023). "Our recent data suggest that Black women have higher protein expression and activation levels of mTOR in their breast tumors than White women." (PMID 35608730, 2022). "In conclusion, AKT1 and RPS6KB2, two important prognostic predictors in the mTOR pathway, are expressed differently in breast tumors in Black and White women." (PMID 35608730, 2022). "In this study of breast tumors from Black and White women, race, grade, HER2 status, and molecular subtype were associated with expression levels of genes we examined in the mTOR pathway in breast tumors." (PMID 35608730, 2022). "Studies with a clinically approved PI3K/mTOR inhibitor (Gedatolisib) in the same model showed marginal efficacy against quiescent breast tumor cells on its own, but substantial synergy with doxorubicin." (PMID 34058066, 2022). "We evaluated associations of race and clinicopathological characteristics with mRNA expression of key mTOR pathway genes in breast tumors." (PMID 35608730, 2022). "Through this analysis, we defined a correlative relationship that enabled us to examine human breast tumors correlations in the context of PI3K/AKT/mTOR axis." (PMID 35413055, 2022). "PI3K/AKT/mTOR axis regulated the ghrelin-induced anti-apoptosis in breast tumor cells treated with cisplatin." (PMID 37303943, 2021). "We also employed the ML-CDN2 model to predict the drug response of several phosphoinositide 3-kinase (PI3K) / mechanistic target of rapamycin (mTOR) signaling pathway inhibitors for TCGA breast tumor samples." (PMID 34059012, 2021). "Ghrelin reduced the CDDP sensitivity by activation of PI3K/AKT/mTOR signaling, Bcl-2 upregulation, and caspase-3 downregulation in breast tumor cells." (PMID 37303943, 2021). "Consistent with prior cell biology studies, breast tumor transcriptomic analyses revealed strong clustering of PI3K/AKT/mTOR and stemness scores with MYC-related biological processes, including proliferation and glycolysis." (PMID 34762647, 2021). "The weak PI3K/AKT/mTOR pathway activity found in the breast tumors expressing low level of FOXO3 protein would be therefore due to a low level of various components of this pathway but not to a high level of PTEN." (PMID 32332845, 2020). "For example, treatment of breast tumor cells with rapamycin reduces the phosphorylation of the mTOR targets S6K and 4EBP1 while simultaneously increasing the phosphorylation of AKT and eIF4E." (PMID 32758183, 2020). "Previous studies have shown that the growth of breast tumor cells was closely related to the activation of PI3K/AKT/mTOR pathway." (PMID 32606352, 2020). "On the other hand, in MCF-7 cells adiponectin induced MAPK phosphorylation, which in turn transactivated ERα and activated mTOR, promoting breast tumor growth." (PMID 31052147, 2019).
breast tumor (continued). "This would explain the lower level of mTOR pathway activation in breast tumor cells compared to AML cells, where secretion takes place and subsequently requires replacement of the proteins through biosynthesis." (PMID 31354733, 2019). "ER and PR levels are inversely correlated with markers of PI3K/AKT/mTOR activation in primary ER+ breast tumors." (PMID 29507656, 2018). "We observed an association between insulin treatment and increased p-mTOR and IGF1R expression of breast tumors, especially in premenopausal women." (PMID 29486734, 2018). "Any insulin use was significantly associated with higher expression of IGF1R (OR = 2.36; 95%CI:1.02–5.52; p = 0.04) and p-mTOR (OR = 2.35; 95%CI:1.13–4.88; p = 0.02) in breast tumors." (PMID 29486734, 2018). "For example, we confirmed the inhibition of PI3K/Akt/mTOR signaling by Tan IIA in MCF-7 breast tumor cells." (PMID 29416003, 2018). "Noteworthy, MDM4 transcript levels are significantly reduced in breast tumors characterized by high mTOR levels." (PMID 28270148, 2017). "In the breast tumor, important members of de-novo lipid synthesis were down-regulated on both the lipid and protein level, and the activated mTOR pathway contributed to inhibition of lipolysis." (PMID 29109428, 2017). "In this study, we describe an analysis framework that utilizes protein inhibition gene expression profiles to probe the activity of the PI3K-Akt-mTOR pathway in primary breast tumors." (PMID 27589846, 2016). "The PI3K/Akt/mTOR signal transduction pathway can regulate gene expression and is crucial in breast tumor cell growth proliferation, metastasis, and apoptosis." (PMID 27391337, 2016). "mTOR phosphorylation status was determined at S2448 residue in vivo by immunohistochemistry in a cohort of more than 400 well-characterized ERα positive breast tumors." (PMID 24887419, 2014). "In human breast tumor cells, a link between autophagic responses to IR and mTOR signaling was reported (31." (PMID 22246348, 2012). "Estimates of eIF4E activity predict sensitivity to mTOR inhibition in cell lines but breast tumours with high estimated eIF4E activity gain changes in eIF4E regulation in order to enhance resistance." (PMID 21320304, 2011). "The other five PLD1-positive breast tumours showed positive expression for phospho-Akt; however, only two of these cases were positive for phospho-mTOR." (PMID 17726467, 2007). "We studied exercise-mediated mTOR pathway activities in breast tumor and adjacent-normal tissue." (PMID 36895729, 2023). "Indeed, GLS inhibition sensitizes breast tumours to CDK4/6 and PRAP inhibition and overcomes breast tumour resistance to mTOR inhibitors." (PMID 34572926, 2021). "It is worth noting that the deletion of autophagy-related gene RB1CC1 could reduce the mitochondrial mass and oxidative respiration capacity of breast tumor cells, as well as inhibit the phosphorylation of mTOR substrate." (PMID 33796128, 2021). "Several clinical studies have been focused on the modulation of phosphoinositide 3-kinase (PI3K)/Akt/mTOR pathway to overcome chemotherapy or hormonotherapy resistance in breast tumors such as everolimus or temsirolimus; this intricated pathway is not yet fully understood and need more studies." (PMID 34489928, 2021). "In addition, receptor tyrosine kinase-dependent ERK1 and ERK2 activation following PI3K/AKT/mTOR inhibition have also been described in preclinical models of HER2-positive breast tumours." (PMID 34204960, 2021). "Interestingly, it was shown that mTOR activity follows matrix stiffness in vivo in both mouse and human breast tumors; i.e., a stiff ECM activates mTOR and supports proliferation, whereas a soft ECM leads to mTOR inhibition and lower proliferating activity." (PMID 33260691, 2020). "Furthermore, genes involved in the G2-M checkpoint and MTOR signaling were differentially expressed in residual breast tumors after Docetaxel treatment when compared to pre-treatment biopsies." (PMID 31063487, 2019).
breast tumor (continued). "Studies demonstrated that the mTOR inhibitor everolimus could sensitize breast tumors to endocrine therapy." (PMID 29070044, 2017). "These previous investigations and our current study in drug-resistant breast tumour cells provide a compelling rationale for investigating the potential of autophagy inhibitors (possibly in combination with mTOR inhibitors) to improve clinical response to chemotherapy." (PMID 27687594, 2016). "In an alternative approach we estimated eIF4E activity, a key effector of mTOR function, and tested the hypothesis that eIF4E activity predicts sensitivity to mTOR inhibition in cell lines and in breast tumours." (PMID 21320304, 2011). "We also found that PLD1 and phospho-Akt are coexpressed in some breast tumours, a fact which could complicate the utility of rapamycin-based therapies, as patients expressing both proteins could differ in sensitivity to mTOR inhibitors." (PMID 17726467, 2007). "Given the importance of the PI3K/Akt/mTOR pathway in breast tumor progression, further research is required to understand the impact of such drugs on the TME, which may reduce cytotoxic effects and enhance the anti-tumor function of other standard treatment regimens." (PMID 37662839, 2023). "Constitutive activation of nuclear factor κB (NF-κB) is frequently observed in PDAC, which suggests that for mt K-ras tumors, zoledronic acid could reduce mTOR resistance and thus enhance the therapeutic efficacy of everolimus, perhaps by inhibiting NF-κB, as previously shown in breast tumors." (PMID 29963262, 2018). "Therefore, together with phospho-p70S6K, phospho-S6 and phospho-4E-BP1, ACSL4 appears to be a useful predictor of mTOR activity and whether breast tumors will respond to the inhibition of mTOR." (PMID 26536660, 2015). "Hence, activating mutations commonly found to impair PI3K/Akt/mTOR regulation in cancer were analyzed in the breast tumor, with none of them being detected." (PMID 24498881, 2014). "Importantly, we also examined whether estimates of pre-treatment eIF4E activity in clinical breast tumours predicted response to the mTOR inhibitor everolimus." (PMID 21320304, 2011). "In certain cases, targeting direct activators such as TBL2 and PRMT5 has been explored as a potential therapeutic strategy for breast tumors, or even the complete inhibition of EGFR/PI3K/AKT and mTOR mediated pathways using natural compounds." (PMID 39950162, 2025). "Our findings identify miR-770-5p as a tumor suppressor in breast tumors, acting as a regulatory switch that targets key players such as EGFR, HER2, IGF1R, as well as downstream effectors including AKT, ERK, and mTOR." (PMID 39051060, 2024). "We investigated the expression of the mTOR pathway components in the TME by analyzing single-cell RNA sequencing (scRNA-seq) data from MC38 colorectal tumors and HER2+ breast tumors sourced from the GEO database (GSE180296 and GSE139492)." (PMID 39766137, 2024). "To date, several studies have addressed the signaling pathways induced by PD-L1 in cancer cells, connecting mTOR/AKT activation with increased PD-L1 activities in cancer cells, including in breast tumor cells." (PMID 37830552, 2023). "Through enhancing PI3K/AKT/mTOR pathway signaling and β‐catenin activity, GPNMB promotes breast tumor initiation and growth mediated by Wnt‐1 signaling." (PMID 38140790, 2023). "We further showed that when the PI3K/mTOR dual inhibitor, gedatolisib, was combined with ICI therapy, there was an ~85% inhibition of growth of PyMT breast tumors." (PMID 34069042, 2021). "Breast tumors that progress on endocrine and CDK4/6 inhibitor therapies are often treated with combination of antiestrogens and mTOR inhibitors or with chemotherapies with nominal success." (PMID 34277427, 2021). "We used established, open-source methods to infer PI3K/AKT/mTOR (henceforth PI3K signaling) and stemness scores from publicly available transcriptomic data from nearly 3,000 primary human breast tumors." (PMID 34762647, 2021).